BCL2 (BCL2 apoptosis regulator)
Diseases named in the same sentence as BCL2 in open-access papers (continued):
Sharing a sentence is not in itself a finding about the gene and the disease.
tongue cancer (7 papers, 2013 to 2025). A malignant neoplasm affecting the tongue. "Three key bioactive compounds in Rumex dentatus (quercetin, taxifolin, and emodin) target 66 common genes linked with cisplatin and tongue cancer, including EGFR, BCL2, and ESR1 as the most important genes identified." (PMID 39863836, 2025). "This activation induces the expression of apoptotic proteins, such as Bax and Bcl-2, leading to the onset of tongue cancer." (PMID 38919616, 2024). "We observed significantly a higher expression of MMP-9, cyclin D1 and Bcl-2 genes in majority of tongue cancer cases and cancer cell lines particularly in HPV−ve cases that show aggressive tumor and worst prognosis." (PMID 26581505, 2015). "Moreover, the downregulation of Bcl-2 gene expression following CaTiO3NPs treatment likely played a central role in promoting apoptotic cell death in HNO-97 tongue cancer cells." (PMID 40464944, 2025). "Red rectangles represent the hit genes involved in the treatment of tongue cancer (TERT, Bcl-2, CDK4/6, CDK2, VEGF, ER, RXR,c-KIT, MET, FGFR, PPAR8, PFFP, MMPs, CDK4, AR, F2, IGFR)." (PMID 39863836, 2025). "In order to examine the effect of Fra-2 silencing on AP-1 target genes associated with aggressive tumorigenesis, we checked the expression of Bcl-2, MMP-9 and cyclin D1 in siRNA treated tongue cancer cell lines." (PMID 26581505, 2015). "We have also examined the role of AP-1 downstream target genes Bcl-2, MMP-9 and Cyclin D1 in tongue cancer." (PMID 26581505, 2015). "As high as 80% (40/50; P = 0.0001) of tongue cancer cases showed strong expression of MMP-9, 68% (34/50; p = 0.06) for Bcl-2 and 78% (39/50; P = 0.0001) for cyclin D1 genes." (PMID 26581505, 2015). "According to these parameters ESR1, EGFR, and BCL2 are deemed core targets within the PPI network, highlighting their significance in potential therapeutic interventions which play an important role in the treatment of tongue cancer." (PMID 39863836, 2025). "Those hub genes involved in pathways of cancer are Bcl2, EGFR, ESR1, MMP9, PPARG, and MMP2 and those involved in PI3K-Akt signaling pathways are Bcl2, EGFR, CDK2, and MCL1 these genes are considered therapeutic targets for tongue cancer." (PMID 39863836, 2025). "Our results showed that the proliferative markers Bcl2 and Pcna were significantly downregulated in tongue dysplastic tissues and tongue carcinomas in animals treated with PL compared to non-treated animals." (PMID 36686704, 2022).
Waldenström macroglobulinemia (7 papers, 2016 to 2025). "Venetoclax has single-agent activity in a broad range of lymphoid neoplasms, with MCL and Waldenstrom macroglobulinemia demonstrating the greatest intrinsic sensitivity to BCL2 inhibition." (PMID 35659041, 2022). "Consistent with this preclinical evidence of a pathobiological role of BCL2, all four patients with Waldenstrom macroglobulinemia who received venetoclax in the phase 1 study in patients with B-NHL attained a PR, with a median PFS and DOR 30 and 25 months, respectively." (PMID 35659041, 2022).
anaplastic thyroid carcinoma (6 papers, 2018 to 2025). "Involvement of VEGF-A with other proliferation regulatory genes such as Notch1 and Bcl-2 has been reported in anaplastic thyroid carcinoma." (PMID 30544959, 2018). "In anaplastic thyroid carcinoma cells, the combination of apigenin and TRAIL resulted in a decreased BCL2 and increased ERK1 and ERK2 expression." (PMID 35965686, 2022).
Arthritis (6 papers, 2016 to 2025). Inflammation of a joint. "In an arthritis model, it has been discovered that the Jak2/Stat3 pathway activates the transcription of antiapoptotic genes, such as Bcl2, and rescues chondrocytes from apoptosis." (PMID 27314053, 2016). "We noted that treatment of the rat model with WJR resulted in a significant reduction in toe swelling, arthritis severity, expression of miRNA-146a, and expression of autophagy genes (ATG5, ATG7, ATG12, Beclin1, LC32, and Bcl2)." (PMID 36440364, 2022). "WJR significantly reduced toe swelling, arthritis scores, and expression of miRNA-146a and autophagy genes (ATG5, ATG7, ATG12, Beclin1, LC32, and Bcl2)." (PMID 36440364, 2022). "M10 ameliorated arthritis in the CAIA model, and inhibited RANKL, WNT5A, and Bcl-2 expression in RA FLS by blocking IL-6 signaling, likely via Janus kinase–STAT3 pathway downregulation." (PMID 29755657, 2018).
B-cell acute lymphoblastic leukemia (6 papers, 2015 to 2025). A neoplasm of lymphoblasts committed to the B-cell lineage, typically composed of small to medium-sized blast cells. "Targeting BCL-2, a key regulator of survival in B-cell malignancies including precursor B-cell acute lymphoblastic leukemia, has become a promising treatment strategy." (PMID 35031695, 2022). "Therefore, we co-expressed Eμ-Myc, which does not require Stat5 for oncogenesis, but can provide complementary signals with Bcl-2 to drive B-cell acute lymphoblastic leukemia in wild-type mice." (PMID 26338970, 2015). "Using a classical murine B-cell acute lymphoblastic leukemia (B-ALL) model, we demonstrate that these HSCs were also poised to produce a burst of B-cell precursors upon expression of Bcl-2 combined with oncogenic Myc." (PMID 26338970, 2015).
cardiac arrest (6 papers, 2009 to 2026). Cessation of breathing and/or cardiac function. "Next, to validate the expression of AKT1, BCL2, and MAPK3 in the large cohort of cardiac arrest patients, we recapitulated gene expression levels of AKT1, BCL2, and MAPK3 in the datasets available from the NCBI, GEO database (GSE29540)." (PMID 28147324, 2017).
cervical adenocarcinoma (6 papers, 2018 to 2025). An adenocarcinoma arising from the cervical epithelium. "We hypothesize that, even with the small number of samples used (randomized selection), there is strong evidence that the selected genes, HOXC6, HOXC8, RARβ, BCL2, and E6/E7, can be used as a pan early cervical adenocarcinoma test." (PMID 40361484, 2025). "In conclusion, this exploratory pilot study, through its robust and holistic analysis, provides evidence that MACC1, HOXC8, RARβ, BCL2, and E6/E7 could be promising molecular markers for the detection of cervical adenocarcinomas." (PMID 40361484, 2025). "Previous study demonstrated that knockdown of PHGDH reduced Bcl‐2 expression in human cervical adenocarcinoma, but the interaction between PHGDH and Bcl‐2 remains unclear." (PMID 33732415, 2021). "PHGDH knockdown in cervical adenocarcinoma resulted in a decrease in Bcl2 expression, suggesting that baseline high PHGDH could also result in increased Bcl2, thereby mitigating the mitochondrial apoptotic response." (PMID 33511334, 2020). "Thirteen genes were found to be differentially expressed in cervical adenocarcinoma samples using microarray databases and literature reports, but only the MACC1, HOXC8, BCL2, and RARβ genes were the most representative of the expressed genes." (PMID 40361484, 2025). "To address potential interferences from the HCT116 cellular background affecting the behavior of the BCL2 TMD mutants, we investigated the homo- and hetero-oligomerization of BCL2 TMD with BAX TMD in the HeLa cervix adenocarcinoma cell line." (PMID 38670940, 2024).
cervical tumor (6 papers, 2009 to 2023). "MiR-7-5p was found to be upregulated in cisplatin-resistant cervical tumor cells, boosting energy production via targeting Bcl-2 and decreasing energy consumption through PARP-1 targeting." (PMID 37098542, 2023). "MiR-143 was shown to regulate the Bcl-2, Bax, and CASP-9 apoptotic genes, which in turn enhanced the cisplatin-mediated death in cervical tumor cells." (PMID 37098542, 2023). "Furthermore, silencing of TCONS_00026907 suppressed the growth of cervical tumors and altered the expression of ELK1, p‐ELK1, C‐fos, Cyclin D1 and Bcl‐2 in vivo." (PMID 28544557, 2017). "Anti-apoptotic Bcl-2 expression is very low in NB and absent in cervix-uterine tumors." (PMID 23382936, 2013).
cholestasis (6 papers, 2014 to 2025). Impairment of the bile flow caused by obstruction within the liver, or outside the liver in the bile duct system. "Similarly, the levels of TC, TBA, γ-GT, TBIL, the expression of TNF-α, TIMP-1, and the BAX/BCL-2 ratio were significantly increased in cholestasis-induced rats compared with the control rats, and these changes were effectively alleviated following treatment with ZYP." (PMID 34539394, 2021). "Compared to the normal group, the cholestasis model group showed significantly reduced PI3K, p-AKT/AKT, and Bcl-2 expression (P < 0.05, P < 0.01), while GSK-3β, caspase-3, and Bax levels were significantly increased (P < 0.05, P < 0.01, P < 0.001)." (PMID 40956833, 2025). "In the GFPG-H group, PI3K, p-AKT/AKT, and Bcl-2 levels were significantly higher (P < 0.05, P < 0.01, P < 0.001), while GSK-3β, caspase-3, and Bax expression was significantly lower (P < 0.05, P < 0.001) compared to the ANIT-induced cholestasis group." (PMID 40956833, 2025).
chordoma (6 papers, 2009 to 2022). Chordomas are rare malignant tumors arising from embryonic remnants of the notochord in axial skeleton. "In chordoma cells, the anti-apoptotic protein Bcl-2 was upregulated in shTMED3 cell group." (PMID 35854294, 2022). "In particular, the knockdown of DEPDC1B resulted in not only a significant upregulation of Caspase3, sTNF-R1, but also downregulation of Bcl-2, CD40, HSP27, IGF-1sR, XIAP, Livin, Survivin in chordoma cells." (PMID 34330893, 2021). "Also, several oncogenes such as BCL2 (11.5-fold), BRAF (9.8-fold), KRAS (4.9-fold), and SRC (2.8-fold) are significantly stronger expressed in the recurrent chordoma cell line." (PMID 34330313, 2021).
chronic heart failure (6 papers, 2011 to 2022). "We previously showed, using this chronic heart failure model, that an overall enhancement of myoblast sheet functionality and survival by antiapoptotic Bcl-2 was associated with improved left ventricular function." (PMID 21541335, 2011). "Siltanen A's experiments showed that BCL2 gene transplantation in rats with chronic heart failure could effectively improve cardiac function, enhance paracrine angiogenic signals, and promote cell proliferation and survival in failing myocardium." (PMID 33273955, 2020). "The Descurainia sophia (L.)Webb ex Prantl might improve cardiac function via regulating the balance between Bax and Bcl-2, blocking the activation of Caspase3 in the chronic heart failure rats." (PMID 31001355, 2019).
clear cell renal cell carcinoma (6 papers, 2009 to 2024). "Moreover, increased expression of anti-apoptotic proteins (Bcl-2, Bcl-xL) and decreased pro-apoptotic protein (Bax and Bad) have been reported to be involved in the resistance of clear-cell renal cell carcinoma cells to imatinib." (PMID 34781823, 2021). "BCL2 and MMP9 have been found to play significant roles in tumor immunity and may serve as potential novel biomarkers and therapeutic targets for immunotherapy of clear cell renal cell carcinoma (ccRCC)." (PMID 39272451, 2024).
ductal carcinoma (6 papers, 2002 to 2022). "Highly BCL2 expression was seen in IDC followed by Infiltrating ductal carcinoma, representing 13/24 (54.2%) and 9/24 (37.5%), correspondingly." (PMID 36299777, 2022). "Second, in the group of HR-positive ductal carcinoma, HIF-1α participates in the most important factor 1 along with SATB1 providing factor loadings opposite to those of AR, ER and BCL2, independently of Ki67 expression (factor 3)." (PMID 22424533, 2012). "When compared with an appropriate control group of ER-positive ductal carcinomas, ILBCs even showed a trend towards a higher frequency of BCL2-negative cases." (PMID 24023670, 2013).
gastric ulcer (6 papers, 2020 to 2025). An ulcerated lesion in the mucosal surface of the stomach. "To further explore the underlying anti-inflammatory and anti-apoptotic molecular mechanisms of the CHRs, we performed IHC to detect the levels of ABCB1, ALOX5, NF-κB, Caspase9, and Bcl-2 in the stomach tissue of the mice with gastric ulcers." (PMID 40283949, 2025). "Some studies have assessed apoptosis markers in models of gastric ulcer as caspase-3, Cit C, and Bcl-2." (PMID 33233494, 2020). "Bcl‐2 expression was reduced in response to gastric ulcer disease." (PMID 34405561, 2021). "Furthermore, treatment with SGD significantly increased the levels of EGF, PGE2, SOD, and Bcl-2 and decreased the levels of TNF-α, TBARS, and caspase-3 in the gastric tissue of rats with ethanol-induced gastric ulcers." (PMID 35449820, 2022).
glomerulonephritis (6 papers, 2016 to 2025). A renal disorder characterized by damage in the glomeruli. "The Bcl-2 was stained in proximal tubules, distal tubules, and interstitial cells in glomerulonephritis patients." (PMID 36699321, 2022). "Vav-BCL2 transgenic mice (BCL2tg) are prone to suffer from follicular lymphoma with age and to develop kidney disease, i.e. glomerulonephritis of an autoimmune type." (PMID 31404120, 2019). "BCL2 transgenic and ETV6/RUNX1;BCL2 double transgenic mice develop a glomerulonephritis phenotype over time, which was displayed by staining of kidney sections." (PMID 31404120, 2019). "In patients with glomerulonephritis, TGF-β had a negative correlation with Bcl-2 but a positive correlation with Bax." (PMID 39858257, 2025).
HCMV infection (6 papers, 2014 to 2022). "In a word, after HCMV infection, the Bax level increased, Bcl-2 and Bcl-2/Bax ratio decreased in cells, indicating that HCMV infection can induce apoptosis." (PMID 33936007, 2021). "During acute HCMV infection, all NK cell subpopulations showed a robust increase in the frequency of proliferating Ki-67+ cells and downregulation of Bcl-2." (PMID 31867015, 2019). "HCMV infection promotes the expression of ATF5 and elevates the Bcl-2 to BAX ratio and enhances anti-apoptosis in U87 cells." (PMID 25120656, 2014).
hepatitis B (6 papers, 2010 to 2023). "The frequency and quantity of CD8 T cells expressing CD38/HLA-DR and Ki-67/Bcl-2 phenotypic markers was analyzed in 20 patients with acute hepatitis B. Samples were collected at multiple time points from onset of disease (HBsAg+, ALT>1000 U/L) to full recovery (HBsAg- at least 1 month after onset)." (PMID 20808900, 2010). "We also found that the ECOG score, hyphemia, complicated systemic diseases (such as hepatitis B and Sjögren syndrome), LDH, aaIPI, and BCL-2 were related to the prognosis of DLBCL." (PMID 36213322, 2022).
hyperlipidemia (6 papers, 2013 to 2023). "The extract of millet leaves can significantly up-regulate the expression of Bcl-2 protein and down-regulate the expression of Bax protein, so as to protect against vascular endothelial oxidative damage caused by hyperlipidemia." (PMID 36770995, 2023). "Based on the pathological gene-sequencing, patients with BCL2 gene fusion mutation are significantly correlative with hyperlipidemia (76.5%, p = 0.006) and hypertriglyceridemia (88.2%, p = 0.002)." (PMID 37384286, 2023). "Through the study, it was found that the extracts of millet leaves can inhibit the apoptosis of vascular endothelial cells induced by hyperlipidemia in model rats by regulating the expression of apoptotic proteins Bax and Bcl-2." (PMID 36770995, 2023). "The liver-protective effect of GT in STZ-NA-induced diabetic rats with hyperlipidemia was through an enhancement in the activation of the compensatory PI3K-Akt and Bcl2 survival-related pathway." (PMID 31170991, 2019).
keloid (6 papers, 2012 to 2021). An irregularly shaped, elevated mark on the skin caused by deposits of excessive amounts of collagen during wound healing. "In the present study, an obvious up-regulation of BCL2 protein both in keloid tissues and fibroblasts was detected, and knockdown of BCL2 inhibited proliferation, metastasis, collagen synthesis and induced apoptosis in KFs." (PMID 33817252, 2020). "BCL2 was up-regulated in keloid tissues and fibroblasts, and BCL2 knockdown promoted the deterioration of KFs." (PMID 33817252, 2020). "In conclusion, herein we have verified for the first time the effects of miR-4328 on the progression of keloids and have identified the miR-4328/BCL2 signaling pathway in KFs." (PMID 33817252, 2020). "The expression of BCL2 was detected and we saw an obvious up-regulation of BCL2 protein both in keloid tissues and fibroblasts." (PMID 33817252, 2020). "In addition, we evaluated the mRNA and protein levels of apoptosis-related genes, including BCL2, Bad, Caspase3 and Caspase9, in keloid fibroblast cells." (PMID 33315500, 2021). "In addition, BCL2 was confirmed to be a target of miR-4328, and the rescue experiment indicated that the inhibitory action of miR-4328 on keloid fibroblast progression was reversed by BCL2 overexpression." (PMID 33817252, 2020). "Thus, our results demonstrated that miR-4328 restrained the deterioration of KFs by targeting BCL2, which sheds new light on miR-4328 as a promising target for keloid development and therapeutic." (PMID 33817252, 2020). "While the detailed mechanism of BCL2 in keloids was still ambiguous." (PMID 33817252, 2020). "Normally, apoptosis-related genes such as Bcl-2 could also mediate apoptosis in fibroblasts, hypertrophic scars, and active keloid tissues." (PMID 23226515, 2012). "We confirmed that BCL2 was a target of miR-4328 and that miR-4328 could inhibit the proliferation, metastasis, collagen synthesis and induce apoptosis in KFs by targeting BCL2, indicating a novel target for prevention and therapy of keloids." (PMID 33817252, 2020). "In this study, tamoxifen treatments altered the expression of anti-apoptotic (Bcl-2) and pro-apoptotic (Bax) proteins, resulting in pCMV6-CDK10-keloid fibroblast cell apoptosis." (PMID 22298115, 2012).